SOST (sclerostin)
Diseases named in the same sentence as SOST in open-access papers (continued):
Sharing a sentence is not in itself a finding about the gene and the disease.
osteoporosis (continued). "Studies in mice and in vitro are rather consistent, showing increased expression of sclerostin after glucocorticoid therapy and a protective role of anti-sclerostin antibodies against glucocorticoid-induced osteoporosis, but in humans, results are so far contradictory." (PMID 36407318, 2022). "Bone formation is also compromised in chronic liver disease as a result of toxic materials, sclerostin, and decreased anabolic hormones, which contribute to osteoporosis in patients with PBC, advanced stage liver cirrhosis, hereditary hemochromatosis, and Wilson disease." (PMID 33807573, 2021). "In particular, Romosozumab (which targets sclerostin) is now an approved therapy for the treatment of osteoporosis and could potentially provide a promising option for MBD treatment, pending further investigation in early phase clinical trials." (PMID 34501423, 2021). "Antagonizing sclerostin is therefore considered a new strategy for the treatment of osteoporosis." (PMID 34361085, 2021). "Thus, a reduction in sclerostin concentration contributes to an increase in bone mineral density (BMD), and anti-sclerostin monoclonal antibodies are currently used in the treatment of osteoporosis." (PMID 34768424, 2021). "This system was capable of transporting SOST siRNA and osteogenic peptide into the cell, and SOST siRNA silenced the osteoporosis related gene SOST (SOST gene inhibits Wnt signaling pathway and reduces osteoblastic differentiation), so as to promote bone formation." (PMID 32602269, 2021). "Since sclerostin, an inhibitor of the Wnt/β-catenin pathway that impairs bone formation, has become an attractive therapeutic target for treating osteoporosis, we wondered if this molecule could also be produced by muscle cells." (PMID 33445754, 2021). "We identified that RA patients with osteoporosis had increased SOST levels." (PMID 34497849, 2021). "Moreover, an outlook comprising future translational applications of anti-sclerostin antibodies in diseases other than osteoporosis is given, highlighting the clinical significance and future scopes of Wnt signaling in these settings." (PMID 33669283, 2021). "Notably, the sclerostin antibody romosozumab has been approved for osteoporosis treatment in 2019 and has promising potential to treat OI." (PMID 33435159, 2021). "Romosozumab, a monoclonal antibody against sclerostin, was developed as an anabolic osteoporosis treatment following the discovery that loss-of-function mutations in the SOST gene, which produces sclerostin, underlies the rare high bone mass disorder sclerosteosis." (PMID 34131654, 2021). "In a mouse model of osteoporosis pseudoglioma syndrome, depletion of sclerostin had an anabolic effect, suggesting that these patients might benefit from Scl-Ab therapy." (PMID 33669283, 2021). "Recently, a sclerostin antibody was approved as a therapeutic agent against osteoporosis." (PMID 34096124, 2021). "These last years, blocking sclerostin (Scl) with an antibody (Scl-Ab) restored bone mass and strength in human postmenopausal osteoporosis and in different animal models of postmenopausal, age-related and disuse osteoporosis." (PMID 34447412, 2021). "The consensus from the majority of these studies indicates that serum sclerostin may act as a predictor of BMD and thus consider this marker to be useful in identifying PCa patients at risk for osteoporosis." (PMID 34290287, 2021). "Moreover, it has been demonstrated in both animal models and clinical experiments that the administration of sclerostin antibody is markedly effective in the prevention of osteoporosis after the decrease in estrogen level." (PMID 34034718, 2021). "Romosozumab, a neutralizing sclerostin antibody, is now approved for osteoporosis treatment." (PMID 32612176, 2020).
osteoporosis (continued). "Although research on the cellular and molecular mechanisms of sclerosteosis and van Buchem disease guided the development of anti-sclerostin antibody to treat osteoporosis, an osteocyte function-targeted therapy for sclerosteosis and van Buchem disease has not yet been developed." (PMID 32733380, 2020). "Anti-sclerostin monoclonal antibody, such as romosozumab, exerts the potent therapeutic effects through an enhancement of bone formation and a suppression of bone resorption in patients with osteoporosis." (PMID 32268570, 2020). "Monoclonal antibodies against sclerostin (romosozumab) have proven in clinical trials to be a very efficient osteo-anabolic approach to the treatment of osteoporosis, since they increase bone formation, bone mass, and bone strength, therefore decreasing markedly fracture risk in treated patients." (PMID 33297501, 2020). "Studies on genetic, molecular, and cellular mechanisms of sclerosteosis and van Buchem disease revealed a role for sclerostin in bone homeostasis, which led to the development of the sclerostin antibody to treat osteoporosis and other bone degenerative diseases." (PMID 32733380, 2020). "And SOST has been used as a new drug target for anti-osteoporosis drug development." (PMID 32793634, 2020). "Moreover, this work opens up avenues toward modulating osteocytic sclerostin production to boost bone mass for diseases, including osteoporosis." (PMID 32612176, 2020). "In contrast, studies of rare bone diseases associated with low or high bone mass (HBM) have provided the basis for a new osteoporosis therapy in the form of Romosozumab, following the discovery that sclerostin – LRP5 regulation of the Wnt signaling pathway plays a major role in bone biology." (PMID 33658983, 2020). "We speculate that this may have consequences for the applicability of sclerostin antibodies in the treatment of glucocorticoid‐induced osteoporosis." (PMID 32803106, 2020). "The canonical wnt signaling pathway has also been studied, Indeed, studies on the canonical wnt signaling sclerostin led to the development of a therapeutic agent directed against the inhibitor sclerostin for the treatment of osteoporosis that was recently approved for use in patients in the US." (PMID 31936261, 2020). "Despite the ambiguous relationship between sclerostin level and aged-related osteoporosis, sclerostin inhibitor was found to increase bone mass and strength in the early stages of treatment in a pre-clinical study, although the effects were significantly reduced after prolonged treatment." (PMID 33363144, 2020). "Recently, osteoporosis treatment using an anti-sclerostin therapy has been introduced." (PMID 31698687, 2019). "Sclerostin has long been considered an effective target for treating osteoporosis." (PMID 30664862, 2019). "This study aimed to assess the relationship between bone mineral density and genotypes of four polymorphisms in previously detected osteoporosis-candidate genes (FDPS rs2297480, LRP5 rs3736228, SOST rs1234612, VKORC1 rs9934438) in postmenopausal Romanian women with primary osteoporosis." (PMID 31774873, 2019). "However, none of these studies have investigated the methylation status of the CpG island of SOST gene in bone tissues of patients with primary osteoporosis." (PMID 30729116, 2019). "In a study regarding the evaluation of the protective effects of Wnt/β-catenin signaling against glucocorticoid-induced osteoporosis, the activation of Wnt/β-catenin signaling in sclerostin knockout mice prevented bone resorption instead of the restoration of bone formation." (PMID 31027235, 2019). "Several anti-sclerostin antibodies have been developed for the treatment of osteoporosis in humans." (PMID 31137666, 2019). "Romosozumab, a humanised monoclonal anti-sclerostin antibody, has been approved in osteoporosis, shows marked improvement in bone formation and bone mineral density, whilst decreasing bone resorption markers, and could be a potential agent for MBD." (PMID 29098361, 2018).
osteoporosis (continued). "Targeting sclerostin expression could therefore be a valuable tool for the prevention of osteoporosis and anti-sclerostin antibodies are already investigated." (PMID 30366476, 2018). "By enhancing the osteogenic potential of the context in which individual therapies such as sclerostin antibodies act it may become possible to both prevent and reverse the age-related skeletal structural deterioration characteristic of osteoporosis." (PMID 27742499, 2017). "In anticipation of phase III trial results which may potentially signify a significant step in achieving market approval here, we review the preclinical and clinical emergence of sclerostin antibody therapies for both osteoporosis and alternative applications." (PMID 27313945, 2016). "In 2001, the breakthrough discovery of the involvement of the Wnt signalling pathway on the regulation of bone remodelling was made possible by the study of rare conditions such as osteoporosis-pseudoglioma syndrome (OPPG) due to LRP5 mutations and sclerosteosis due to SOST defects." (PMID 27533615, 2016). "Results differ on changes in serum sclerostin levels in relation to osteoporosis." (PMID 27666393, 2016). "Understanding of the molecular mechanisms involved in promoting bone density has been important to the development of multiple drug therapies for osteoporosis, such as the capthepsin K inhibitors Odanacatib and Balicatib, anti-SOST antibodies, anti-Dkk1 antibodies, and GSK3β and Sfrp1 inhibitors." (PMID 27483347, 2016). "Potential clinical challenges are also explored as well as ongoing developments that may impact on the eventual clinical application of sclerostin antibodies as an effective treatment of osteoporosis." (PMID 27313945, 2016). "In this article, we review three rare skeletal disorders with case descriptions, pycnodysostosis and the craniotubular hyperostoses sclerosteosis and van Buchem disease that led to the development of cathepsin K and sclerostin inhibitors, respectively, for the treatment of osteoporosis." (PMID 26892377, 2016). "Anti-sclerostin antibodies such as romosozumab and blosozumab are the alternative drugs of mechanical strain-related stimulus that can overcome the mechanostat-related limitation of osteoporosis therapy." (PMID 25954248, 2015). "We hypothesized that a combination of a pharmacologic dose of Sclerostin Antibody (Scl-Ab) and running training might have a synergetic effect in osteoporosis treatment." (PMID 28377954, 2015). "Drugs with limited anti-tumor activity but which are anabolic for bone include intermittent parathyroid hormone and antibodies that neutralize the WNT inhibitors DKK1 and sclerostin, as well as the activin A blocker sotatercept and the osteoporosis drug strontium ranelate." (PMID 25757219, 2014). "The SPR4-peptide mediated suppression of sclerostin and improvement in energy metabolism may have therapeutic utility for osteoporosis, obesity and diabetes." (PMID 24839967, 2014). "This is not the first time that common variation within a gene that has previously been identified as underlying a rare monogenetic form of osteoporosis and/or high bone mass has been implicated in BMD regulation, other examples including the SOST, CLCN7 and LRP5 genes." (PMID 24176111, 2013). "For example, sclerostin may provide an alternative therapeutic target during the acute phase of injury as a prevention strategy to prevent initial, rapid osteoporosis, and to improve rehabilitation outcomes in chronic stages." (PMID 25419534, 2013). "Its gene product, Sclerostin, is a key negative regulator of bone formation and might therefore serve as a target for the anabolic treatment of osteoporosis." (PMID 23638027, 2013). "It is conceivable that the premature expression of SOST in osteoporotic stem cells auto-inhibits proliferation and self-renewal of hMSC-OP and thereby leads to the reduced ratios of formation to resorption observed in primary osteoporosis." (PMID 23028809, 2012).
osteoporosis (continued). "Antibodies that block sclerostin are therefore being evaluated for osteoporosis treatment." (PMID 21438671, 2011). "The data suggest a potential major role for sclerostin in mediating the bone response to unloading and propose it may be a promising target for preventing disuse osteoporosis." (PMID 20981340, 2010). "Although these studies are short term, they suggest that sclerostin inhibition resulting in increased bone formation may be useful clinically in osteoporosis and fracture healing." (PMID 20981340, 2010). "Additionally, exercise may impact bone hormonal signaling, potentially lowering sclerostin and linking mechanical loading to osteoporosis." (PMID 41733896, 2026). "We found that higher serum sclerostin levels were significantly associated with the presence of sarcopenia, particularly through an inverse correlation with grip strength, whereas no such association was observed with osteoporosis." (PMID 41594249, 2026). "Further cellular assays confirmed that sera from vaccinated mice contain anti-SOST antibodies capable of inhibiting osteoclast activity and promoting osteoblast function, thereby restoring the balance between bone resorption and formation disrupted in osteoporosis." (PMID 41403949, 2025). "Moreover, histological examination revealed a normal cellular structure and no lesions in the internal organs following treatment with Apc001OA and Apc001OA‐d6, suggesting that the two sclerostin aptamers are safe for the internal organs of male osteoporosis mice." (PMID 40464222, 2025). "Multiple studies have reported lower sclerostin levels in patients with osteoporosis or osteopenia compared to individuals with normal bone mass, a finding also observed in postmenopausal women, which may be attributed to an age-related decline in osteocyte number." (PMID 41367909, 2025). "Therefore, we speculate that sclerostin may be involved in osteoporosis independently of bone metabolism markers." (PMID 39720253, 2024). "Therefore, we speculate that sclerostin is not only involved in the pathogenesis of diabetes, but also plays an important role in osteoporosis through glucose metabolism." (PMID 39720253, 2024). "As a result, we speculate that sclerostin can be used as a biomarker for osteoporosis." (PMID 39720253, 2024). "Since inhibition of sclerostin would activate Wnt signaling, and this might benefit bone formation as well as potentially benefit neurons, synaptic plasticity, and microglia, Romosozumab might also be a good candidate for both osteoporosis and ADRD therapy." (PMID 38285083, 2024). "Sclerostin measurements could become a useful clinical index for diagnosis of osteoporosis." (PMID 38352898, 2024). "In addition, considering the proven efficacy of romosozumab (an anti-sclerostin antibody) in osteoporosis treatment, anti-sclerostin treatment may effectively promote the healing of the vertebrae." (PMID 36864451, 2023). "Therefore, SOST and Dkk-1 have become very potent targets for the treatment of osteoporosis." (PMID 36979418, 2023). "Furthermore, whether anti-SOST monoclonal antibodies can delay liver damage while treating severe osteoporosis is worth investigating." (PMID 37091847, 2023). "Therefore, the process of osteoporosis might increase not only osteoclast activity but also sclerostin, an antagonist of osteoblasts." (PMID 36363523, 2022). "Furthermore, serum sclerostin was lower in patients with previous radiological evidence of fracture (127 pg/mL vs. 176 pg/mL, Mann–Whitney, p < 0.05) and previous history of osteoporosis (118 pg/mL vs. 153 pg/mL, Mann–Whitney, p < 0.05)." (PMID 36612090, 2022). "Therefore, sclerostin may be a potential therapeutic target in hyperthyroidism related osteoporosis." (PMID 35464058, 2022).
osteoporosis (continued). "As a consequence, in TM population the Wnt/ß-catenin pathway could be involved in the pathogenesis of osteoporosis and negative modulators of this signaling system, such as Dickkopf-1 and sclerostin, have also been associated with BMD in TM patients." (PMID 35243531, 2022). "Thus, targeting sclerostin with an antisclerostin antibody could be beneficial for the treatment of glucocorticoid-induced osteoporosis." (PMID 35160258, 2022). "A negative feedback loop on sclerostin may exist, which is activated in osteoporosis or in other conditions causing a worse bone mineral density." (PMID 35705746, 2022). "We investigated whether DKK-1 and SOST serum levels are biomarkers of osteoporosis in RA patients." (PMID 34497849, 2021). "Secondly, we did not examine bone morphometric parameters in middle-aged or elderly mice, which may be more clinically relevant for osteoporosis studies, although sclerostin inhibition is also being investigated for use in children with rare bone diseases such as osteogenesis imperfecta." (PMID 33339872, 2020). "And the pathogenesis of osteoporosis may be partially attributed to the demethylation of SOST gene." (PMID 30729116, 2019). "Hence, strategies for reducing circulating sclerostin, for example by targeting glycosylation enzymes as suggested by our GWAS results, may prove valuable in treating osteoporosis." (PMID 31170332, 2019). "In conclusion, we reported for the first time the importance of identified allelic combinations of SOST rs1234612, PTH rs7125774, FDPS rs2297480, and GGPS1 rs10925503 gene variants for evaluation of the individual resistance or sensitivity to BPs treatment of osteoporosis." (PMID 31437227, 2019). "This provides a new direction to better understand the cellular and molecular mechanisms of bone response to mechanical stimuli, as well as the roles of key bone regulatory proteins, such as RANKL and sclerostin, which may be the target of anti-osteoporosis drugs." (PMID 29581909, 2018). "However, taking into consideration the anabolic effect of anti-sclerostin on bone metabolisms and its efficacy in the treatment of osteoporosis, there is a promise that anti-sclerostin could enhance spinal fusion." (PMID 30126106, 2018). "Thus, the human disease provided not only the model for the identification of sclerostin and its importance in bone remodeling, but could also predict the response of patients with osteoporosis to sclerostin inhibitors." (PMID 26892377, 2016). "This study provides important, yet intriguing, information about the long-term effects of treatment with sclerostin inhibitors and raises questions about potential bone-site specificity of treatment in the long term as well as of optimal duration of treatment of humans with osteoporosis with Scl-Ab." (PMID 27016922, 2016). "Moreover, the sclerostin single chain fragments (Scl-scFv; 35 KD) were observed to increase bone density, enhance bone formation, and improve bone microstructure in a rat preclinical model of osteoporosis." (PMID 27313945, 2016). "Finally, if complete deletion of SOST might be deleterious to cartilage, attention needs to be paid to the joints of patients with osteoporosis who may require anti-sclerostin antibody therapy." (PMID 25656376, 2015). "We speculate that, in the context of high population prevalence of hyperthyroidism and its recurrent nature, our results might be clinically relevant in terms of potential benefits of prevention and treatment hyperthyroidism-induced osteoporosis with antibodies to sclerostin." (PMID 26366174, 2015). "Therefore, agents regulating osteocyte functions such as sclerostin secretion could be effective in the treatment of osteoporosis." (PMID 25652541, 2015). "Interestingly, the monoclonal antibody for sclerostin has shown positive effects on osteoporosis, indicating that it may facilitate cementogenesis and benefit the treatment of cementum related diseases." (PMID 24152444, 2013).